MT-CO3 (mitochondrially encoded cytochrome c oxidase III)
Description:
Component of the cytochrome c oxidase, the last enzyme in the mitochondrial electron transport chain which drives oxidative phosphorylation. The respiratory chain contains 3 multisubunit complexes succinate dehydrogenase (complex II, CII), ubiquinol-cytochrome c oxidoreductase (cytochrome b-c1 complex, complex III, CIII) and cytochrome c oxidase (complex IV, CIV), that cooperate to transfer electrons derived from NADH and succinate to molecular oxygen, creating an electrochemical gradient over the inner membrane that drives transmembrane transport and the ATP synthase. Cytochrome c oxidase is the component of the respiratory chain that catalyzes the reduction of oxygen to water. Electrons originating from reduced cytochrome c in the intermembrane space (IMS) are transferred via the dinuclear copper A center (CU(A)) of subunit 2 and heme A of subunit 1 to the active site in subunit 1, a binuclear center (BNC) formed by heme A3 and copper B (CU(B)). The BNC reduces molecular oxygen to 2 water molecules using 4 electrons from cytochrome c in the IMS and 4 protons from the mitochondrial matrix.
Synonyms: COIII; COX3; CO3; formerly MTCO3
Tractability: Small molecule: a structure with a bound ligand is known. Antibody: UniProt predicts a signal peptide or a membrane-spanning region.
Gene: Protein-coding gene on chromosome MT (9,207 to 9,990, forward strand). Ensembl gene ENSG00000198938.
Subcellular location: Mitochondrion inner membrane
Pathways (Reactome):
Metabolism: Complex IV assembly; Respiratory electron transport
Cellular responses to stimuli: Cytoprotection by HMOX1
Metabolism of proteins: Mitochondrial translation termination
Gene Ontology:
Molecular function: protein binding; cytochrome-c oxidase activity; electron transfer activity
Biological process: respiratory chain complex IV assembly; cellular respiration; mitochondrial electron transport, cytochrome c to oxygen; aerobic electron transport chain; proton transmembrane transport; respiratory electron transport chain
Cellular component: mitochondrial inner membrane; mitochondrial membrane; mitochondrion; respiratory chain complex IV; membrane
Gene-disease validity (ClinGen):
ClinGen rates the evidence that MT-CO3 causes each of these diseases.
mitochondrial disease (mitochondrial): Definitive.
Leigh syndrome (mitochondrial): Limited. A progressive neurological disease defined by specific neuropathological features associating brainstem and basal ganglia lesions.
Homologues: Orthologues: chimpanzee MT-CO3 (97% identical), rat Mt-co3 (88% identical), mouse mt-Co3 (87% identical), pig COX3 (87% identical), rabbit MT-CO3 (87% identical), macaque COX3 (86% identical), guinea pig MT-CO3 (84% identical), tropical clawed frog COX3 (81% identical), zebrafish mt-co3 (81% identical), Drosophila melanogaster mt:CoIII (65% identical), Caenorhabditis elegans COX3 (43% identical).
Diseases named in the same sentence as MT-CO3 in open-access papers:
MT-CO3 is named in the same sentence as 66 diseases in open-access papers, as found by Europe PMC text mining. Sharing a sentence is not in itself a finding about the gene and the disease. The quoted sentences say what the papers report.
COVID-19 (4 papers, 2023 to 2024). A disease caused by infection with severe acute respiratory syndrome coronavirus 2. "Therefore, the upregulation of MT-CO3 is reasonable given that COVID-19 vaccination induces B-cell-mediated humoral immunity." (PMID 36936955, 2023). "Furthermore, SARS-CoV-2 natural infection leads to differential MT-CO3 gene expression, further demonstrating that immunological response induced by COVID-19 vaccination may change MT-CO3 expression." (PMID 36936955, 2023). "Although little has been written about the specific role of MT-CO3 in CD4+ T cells, according to the important role of MT-CO3 gene in the immune response and its involvement in aerobic respiratory energy supply, MT-CO3 gene may show differential expression after COVID-19 vaccination." (PMID 36936955, 2023).
Leber hereditary optic neuropathy (4 papers, 2014 to 2023). Leber's hereditary optic neuropathy (LHON) is a mitochondrial neurodegenerative disease affecting the optic nerve and often characterized by sudden vision loss in young adult carriers. "Despite conflicting reports on its association with Leber Hereditary Optic Neuropathy, direct functional consequences of G78S variation in MT-CO3 gene is not evident." (PMID 36758048, 2023).
MELAS syndrome (3 papers, 2015 to 2023). MELAS (Mitochondrial myopathy, encephalopathy, lactic acidosis, and stroke) syndrome is a rare progressive multisystemic disorder characterized by encephalomyopathy, lactic acidosis, and stroke-like episodes. "MT-CO3, which codes for cytochrome C oxidase subunit III, is responsible for diseases such as LHON and MELAS syndrome also under regulation of these miRNA." (PMID 25695052, 2015).
Parkinson disease (3 papers, 2020 to 2022). A progressive degenerative disorder of the central nervous system characterized by loss of dopamine producing neurons in the substantia nigra and the presence of Lewy bodies in the substantia nigra and locus coeruleus. "In general, levodopa inhibited the growth of ESCC cells through regulating pathways involved in oxidative phosphorylation, NAFLD, and Parkinson disease, down-regulating the levels of SDHD, NDUFS4, and MT-CO3, and inhibiting oxidative phosphorylation." (PMID 33101026, 2020).
asthenozoospermia (2 papers, 2022 to 2024). "A 2-fold decrease of expression of genes related to mitochondrial cytochrome oxidase subunits and asthenozoospermia was documented (mt-Co2, mt-Co3)." (PMID 38650655, 2024).
Leigh syndrome (2 papers, 2012 to 2023). "In this study, we expand the clinical manifestation of the MT-CO3-related Leigh syndrome." (PMID 37095367, 2023).
tongue squamous cell carcinoma (2 papers, 2022 to 2023). A squamous cell carcinoma that arises from the tongue. "Interestingly, miR-5787 was suggested to regulate cisplatin chemoresistance of tongue squamous cell carcinoma (TSCC) by downregulating MT-CO3 which in turn disrupted glucose metabolism." (PMID 35392560, 2022).
adrenocortical carcinoma (1 paper, 2019). "Interestingly, TCGA RNA sequencing data also identified an association of higher MT-CO3 expression levels with increased overall survival in four cancer types, including adrenocortical carcinoma (ACC), kidney chromophobe (KICH), low-grade glioma (LGG), and pancreatic adenocarcinoma (PAAD)." (PMID 31534516, 2019).
Alzheimer disease (1 paper, 2023). A progressive, neurodegenerative disease characterized by loss of function and death of nerve cells in several areas of the brain leading to loss of cognitive function such as memory and language. "MT-CO3 is involved in mitochondrial energy metabolism and is intimately associated with the pathogenesis of Alzheimer’s disease." (PMID 37106826, 2023).
developmental delay (1 paper, 2024). "A boy with hypotonia and developmental delay had the m.9984G>A p.(Gly260Ter) variant which affects the penultimate codon of the MT‐CO3 gene." (PMID 39095335, 2024).
epilepsy (1 paper, 2023). A brain disorder characterized by episodes of abnormally increased neuronal discharge resulting in transient episodes of sensory or motor neurological dysfunction, or psychic dysfunction. "Case 9 is a girl with no family history of epilepsy and a previously undescribed variant in the mitochondrial gene, the cytochrome C oxidase 3 (MT-CO3) gene." (PMID 37095367, 2023).
esophageal squamous cell carcinoma (1 paper, 2022). Esophageal squamous cell carcinoma (ESCC) is a type of esophageal carcinoma (EC) that can affect any part of the esophagus, but is usually located in the upper or middle third. "Levodopa was shown to inhibit the proliferation of esophageal squamous cell carcinoma (ESCC) via down-regulating the levels of oxidative phosphorylation proteins which includes MT-CO3, SDHD and NDUFS4." (PMID 35392560, 2022).
gout (1 paper, 2018). A condition characterized by painful swelling of the joints, which is caused by deposition of urate crystals. "MT-CO3 mutations increase reactive oxygen species (ROS), which activates inflammasome, the link between urate crystals and gout." (PMID 29976239, 2018). "Altogether, this evidence suggests that these four potentially pathogenic MT-CO3 alleles may be involved in the development of gout." (PMID 29976239, 2018). "In addition to gout, potentially pathogenic MT-CO3 alleles were associated with higher HDL in our cohort." (PMID 29976239, 2018). "Altogether, these findings suggest that MT-CO3 alleles might mediate gout through respiratory complex IV dysfunction and subsequent ROS and inflammasome activation." (PMID 29976239, 2018).
Huntington disease (1 paper, 2019). Huntington disease (HD) is a rare neurodegenerative disorder of the central nervous system characterized by unwanted choreatic movements, behavioral and psychiatric disturbances and dementia. "MT-CO3 has also been implicated in AD, Huntington’s disease (HD), and Parkinson’s disease (PD); however, no previous study has reported an association between MT-CO3 and brain aging." (PMID 31779658, 2019).
leprosy (1 paper, 2023). Leprosy is a chronic infectious disease affecting primarily the skin and peripheral nervous system. "Furthermore, we identified 26 heteroplasmic variants shared between the T and L poles that are present in the MT-RNR2, MT-ND1, MT-ND5, MT-CYB, MT-CO2 and MT-CO3 genes, suggesting that these genes may be correlated with the susceptibility and severity of leprosy." (PMID 38062538, 2023).
multiple symmetric lipomatosis (1 paper, 2018). A rare subcutaneous tissue disease characterized by growth of symmetric non-encapsulated masses of adipose tissue mostly around the face and neck with variable clinical repercussions (e.g. reduced neck mobility, compression of respiratory structures). "The association between MT-CO3 (encoding a subunit of complex IV) and HDL metabolism was further strengthened by the association between increased HDL and multiple symmetric lipomatosis, a disease characterized by complex IV dysfunction." (PMID 29976239, 2018).
obsessive-compulsive disorder (1 paper, 2015). A disorder characterized by the presence of persistent and recurrent irrational thoughts (obsessions), resulting in marked anxiety and repetitive excessive behaviors (compulsions) as a way to try to decrease that anxiety. "The expression of other 5 protein-coding mitochondrial-encoded genes, MT-ND1, MT-ND5, MT-CO3, MT-ATP6, MT-ATP8, was found associated with the maternal psychopathology diagnosis of maternal obsessive compulsive disorder, maternal weight and with infant birth measures." (PMID 26418562, 2015).
oncocytic tumors (1 paper, 2012). "Conversely, the MT-CO3 gene had 0/67 non-silent variants in the oncocytic tumors but 12/107 in the general cancers (p value = 0.004)." (PMID 22299657, 2012).
ovarian carcinoma (1 paper, 2022). A malignant neoplasm originating from the surface ovarian epithelium. "The MT-CO3 G9477A (V91I) missense polymorphism detected in the investigated material was described in serum ovarian cancer and was found to increase the risk of this cancer." (PMID 36292984, 2022).
schwannoma (1 paper, 2021). A benign, usually encapsulated slow growing tumor composed of Schwann cells. "Seven heteroplasmic mutations were identified across schwannoma samples with 3 missense mutations identified in MT-CO3, MT-ND4, and MT-CYTB." (PMID 34337412, 2021).
Sepsis (1 paper, 2024). Sepsis is defined as life-threatening organ dysfunction caused by a dysregulated host response to infection. "In conclusion, our study provides important data on the clinical value of Cell-free DNA, represented here by mt-ND1, mt-CO3 and n-Rps18 in patients with sepsis." (PMID 38803503, 2024).
cancer (11 papers, 2009 to 2025). A tumor composed of atypical neoplastic, often pleomorphic cells that invade other tissues. "In this study, using a cancer model, we showed that miR-5787 enhanced the translation of MT-CO3 in a posttranscriptional manner." (PMID 31534516, 2019). "Note, the targeted MT-CO3 gene sequence was selected as being not mutated in the mitochondrial genome of cancer patients." (PMID 30914716, 2019).
infection (7 papers, 2016 to 2025). The state of being infected such as from the introduction of a foreign agent such as serum, vaccine, antigenic substance or organism. "Among the most significant differentially expressed genes, we noticed a downregulation of genes associated with cell death during infection, including FosL1, Mt-Co3, and Mt-Co1, among others." (PMID 35984745, 2022).
tumor (4 papers, 2017 to 2022). "On a similar note, MT-CO3 (down regulated in this study), also involved in the metabolism process specifically the oxidative phosphorylation, influence abnormal energy metabolism and facilitate the growth of tumor cells." (PMID 35392560, 2022). "Further studies about the relationship of SDHC, SDHD, MTCO3, and NDUFV3 in MQ-induced anti-tumor effect will be applied." (PMID 32850358, 2020).
brain disorder (1 paper, 2023). A disease affecting the brain or part of the brain. "Mitochondrial dysfunction has long been implicated in the pathogenesis of PD, and several studies have identified mutations in mt-Co2, mt-Co2, mt-Co3, and mt-Atp6 associated with various clinical brain disorders." (PMID 38041169, 2023).
MT-CO3 also shares sentences with these, for which no sentence is quoted: atherosclerosis (3 papers); breast carcinoma (2); cardiomyopathy (2); mitochondrial disease (2); adenoma (1); Alpers Disease (1); amyotrophic lateral sclerosis (1); autoimmune polyendocrinopathy (1); brain ischemia (1); brain tumors (1); cardiac diseases (1); co-infection (1); colorectal carcinoma (1); dilated cardiomyopathy (1); endothelial dysfunction (1); glioblastoma (1); glomerulonephritis (1); IgA nephropathy (1); ischemia (1); keloid (1); lactic acidosis (1); Lethal Infantile Mitochondrial Disease (1); low grade glioma (1); lupus nephritis (1); malaria (1); male infertility (1); membranous glomerulonephritis (1); meningioma (1); metabolic disease (1); Mitochondrial myopathy (1).
A further 11 diseases each share a sentence with MT-CO3 in 1 paper.